KCMF1 (potassium channel modulatory factor 1)
Description:
E3 ubiquitin-protein ligase which accepts ubiquitin from an E2 ubiquitin-conjugating enzyme and then transfers it to targeted substrates, promoting their degradation by the proteasome. Together with UBR4, component of the N-end rule pathway: ubiquitinates proteins bearing specific N-terminal residues that are destabilizing according to the N-end rule, leading to their degradation. Does not ubiquitinate proteins that are acetylated at the N-terminus. Together with UBR4, part of a protein quality control pathway that catalyzes ubiquitination and degradation of proteins that have been oxidized in response to reactive oxygen species (ROS): recognizes proteins with an Arg-CysO3(H) degron at the N-terminus, and mediates assembly of heterotypic 'Lys-63'-/'Lys-27'-linked branched ubiquitin chains on oxidized proteins, leading to their degradation by autophagy. Catalytic component of the silencing factor of the integrated stress response (SIFI) complex, a multiprotein complex that turns off the mitochondrial stress response after a specific stress event has been resolved. The SIFI complex ubiquitinates and degrades (1) components of the HRI-mediated signaling of the integrated stress response, such as DELE1 and EIF2AK1/HRI, as well as (2) unimported mitochondrial precursors such as ABHD10. Within the SIFI complex, UBR4 initiates ubiquitin chain that are further elongated or branched by KCMF1.
Synonyms: PCMF; FIGC; ZZZ1; DEBT91; DKFZP434L1021
Tractability: Antibody: its Gene Ontology location is reachable by antibodies, with high confidence. PROTAC: ubiquitination databases record sites on it; its protein half-life has been measured.
Gene: Protein-coding gene on chromosome 2 (84,970,644 to 85,059,472, forward strand). Ensembl gene ENSG00000176407.
Subcellular location: Cytoplasm; Late endosome; Lysosome
Subcellular location (Human Protein Atlas): Cytosol; Nucleoplasm
Pathways (Reactome):
Immune System: Neutrophil degranulation
Gene Ontology:
Molecular function: protein binding; ubiquitin protein ligase activity; zinc ion binding
Biological process: HRI-mediated signaling; negative regulation of HRI-mediated signaling; proteasome-mediated ubiquitin-dependent protein catabolic process; protein K48-linked ubiquitination; protein K63-linked ubiquitination; response to oxidative stress; ubiquitin-dependent protein catabolic process; synaptic signaling; protein ubiquitination
Cellular component: cytoplasm; cytosol; late endosome; lysosome; ubiquitin ligase complex; extracellular region; ficolin-1-rich granule lumen; plasma membrane; synapse
Genetic constraint (gnomAD): Loss-of-function variants: 2 observed, 25.72 expected, observed/expected ratio (o/e) 0.0778, 90% interval 0.031 to 0.25. The upper end of that interval is the gene's LOEUF score, 0.25, which puts it in group 1 of 6, group 1 being the genes least tolerant of losing a copy. Missense variants: 216 observed, 357.48 expected, observed/expected ratio (o/e) 0.6, 90% interval 0.54 to 0.68. Synonymous variants: 103 observed, 121.4 expected, observed/expected ratio (o/e) 0.85, 90% interval 0.72 to 1.
Homologues: Orthologues: chimpanzee KCMF1 (100% identical), pig KCMF1 (99% identical), dog KCMF1 (99% identical), macaque KCMF1 (99% identical), mouse Kcmf1 (97% identical), guinea pig KCMF1 (97% identical), rat Kcmf1 (95% identical), tropical clawed frog kcmf1 (92% identical), zebrafish kcmf1 (90% identical), Drosophila melanogaster Kcmf1 (58% identical), Caenorhabditis elegans kcmf-1 (33% identical), Drosophila melanogaster CG15286 (31% identical), and 5 more.
Diseases named in the same sentence as KCMF1 in open-access papers:
KCMF1 is named in the same sentence as 9 diseases in open-access papers, as found by Europe PMC text mining. Sharing a sentence is not in itself a finding about the gene and the disease. The quoted sentences say what the papers report.
gastric cancer (2 papers, 2014 to 2025). A primary or metastatic malignant neoplasm involving the stomach. "KCMF1 (potassium channel modulatory factor 1, also known as FIGC (bFGF-induced in gastric cancer)) is a 381 amino-acid protein-coding gene expressed at different levels in virtually all tissues." (PMID 25563226, 2014). "KCMF1 has been reported to be down-regulated in Ewing’s sarcoma cell lines after the over expression of CD99 and up-regulated in gastric cancer (KCMF1 as a CD99-regulated putative metastasis suppressor gene)." (PMID 25563226, 2014). "KCMF1, a potassium channel regulatory factor, promotes the development of pancreatic cancer by modulating MAPK levels and driving cell proliferation, and it is also elevated in gastric cancer via FGF2 signaling pathway." (PMID 39661479, 2025).
pancreatic cancer (2 papers, 2014 to 2025). "The down-regulation of KCMF1 in vivo reduced preneoplastic changes in the transforming growth factor-α transgenic pancreatic cancer model." (PMID 25563226, 2014). "However, the temporal and spatial expression of KCMF1 preneoplastic lesions of pancreatic cancer in human and murine carcinoma argues against a tumor-suppressive function of KCMF1 in vivo." (PMID 25563226, 2014).
lung carcinoma (1 paper, 2025). "The “new” autoantibodies in our panel target TAAs like DCTPP1, GIMAP4, WWP2, MGMT, KCMF1, and GDA, which have demonstrated links to lung cancer pathogenesis." (PMID 39661479, 2025).
maturity-onset diabetes (1 paper, 2014). "This SNP is in the KCMF1 (potassium channel modulatory factor 1) gene which is known to associate with maturity-onset diabetes of the young." (PMID 25368629, 2014).
cancer (3 papers, 2014 to 2025). A tumor composed of atypical neoplastic, often pleomorphic cells that invade other tissues. "The discovery of a convergence point for multiple quality control pathways may explain why aneuploid cells are especially sensitive to loss of UBR4 or KCMF1 and identifies a potential vulnerability across many cancers." (PMID 39879985, 2025). "KCMF1 and GDA, not previously reported in LUAD, have emerged as potential cancer biomarkers." (PMID 39661479, 2025).
tumor (3 papers, 2014 to 2026). "KCMF1 was consistently upregulated in tumor tissues and was associated with poor patient survival." (PMID 41938511, 2026). "Single-cell and spatial transcriptomic analyses further investigated KCMF1's expression and its functional role in the tumor microenvironment." (PMID 42118414, 2026). "Single-cell analysis identified KCMF1-positive malignant cells as hubs of intercellular communication, while spatial transcriptomics confirmed its enrichment in malignant regions, underscoring its role in tumor-stroma interactions." (PMID 42118414, 2026).
KCMF1 also shares sentences with these, for which no sentence is quoted: Ewing sarcoma (1 paper); hepatocellular carcinoma (1); renal cell carcinoma (1).